CHSY1 (chondroitin sulfate synthase 1)
Diseases named in the same sentence as CHSY1 in open-access papers (continued):
Sharing a sentence is not in itself a finding about the gene and the disease.
tumor (16 papers, 2015 to 2025). "Further analysis showed that CCNG2 and CHSY1 were significantly associated with the tumor immune microenvironment." (PMID 40570725, 2025). "Immunofluorescence results showed that the PLGA-loaded Artemisinin + ICG probe decreased CHSY1 and PD-L1 expression in tumor tissues more significantly than Artemisinin alone." (PMID 37749638, 2023). "Immunofluorescence results showed that Artemisinin decreased the expression of CHSY1 and PD-L1 in tumor tissues, while the combination of anti-PD1 increased this trend." (PMID 37749638, 2023). "LINC01094 acts as a competitive endogenous RNA in ccRCC and plays a tumor-promoting contribution to the progress of ccRCC through the microRNA 224-5p/chondroitin synthase 1 (CHSY1) regulatory axis." (PMID 36824662, 2023). "Since human samples and cellular experiments cannot adequately simulate the tumor microenvironment, we demonstrated in vivo that CHSY1 promoted CD8+ T cell exhaustion and liver metastasis from CRC." (PMID 37749638, 2023). "Immunostaining of excised tumor sections revealed an increased percentage of Ki67-positive cells in CHSY1-overexpressing tumor tissue." (PMID 32019907, 2020). "Consistent with our findings, it has been reported that LINC01094 plays its pro-tumor role in the development of ccRCC by regulating the miR-224-5p/CHSY1 axis." (PMID 33173535, 2020). "Our results showed that overexpression of CHSY1 significantly increased tumor volume in the 3 weeks after transplantation." (PMID 32019907, 2020). "Targeting PDGFR pathway with small molecule inhibitors significantly inhibited CHSY1-mediated GBM tumor growth in murine models." (PMID 32019907, 2020). "Altogether, these results shed light on the role as tumor promotor of CHSY1 which may possess synergistic effects with MCM8 on CRC." (PMID 37710286, 2023). "Moreover, immunofluorescence microscopy revealed that PDGFRA was highly expressed on the cell membrane of CHSY1-overexpressing GL261 tumor tissue sections." (PMID 32019907, 2020). "The oncogenic components, namely, ALDH1B1, ALDH1L2, CHSY1, CSGALNACT2, and GPX8, were progressively upregulated in more aggressive tumors, while the tumor suppressor hubs FBP1 and HPGD were downregulated as tumor aggressiveness increased." (PMID 40626022, 2025). "Immunohistochemical results from in vivo experiments further validated that knockdown of CHSY1 increased the expression of CD8+ T cells and decreased the expression of PD-L1 in the tumor microenvironment." (PMID 37749638, 2023). "Four of these intersecting genes, including PTPN1, CHSY1, SIAH1, and CCSAP, were correlated with tumor cell proliferation, migration, and invasion, and we therefore further confirmed their expression levels via RT-qPCR." (PMID 35610725, 2022). "Through miR-224-5p/CHSY1 axis, LINC01094 activated by FOXM1 played its tumor-promoting role in the development of CCRCC." (PMID 36727070, 2022). "Chondroitin sulfate synthase-1 (CHSY-1) is an enzyme that synthesizes chondroitin sulfate, which is abundant in both the ECM and cell surface of the tumor." (PMID 33440657, 2021). "Increased CHSY1 and CSGALNACT2 expression remodels the extracellular matrix (ECM) through glycosaminoglycan biosynthesis, whereas downregulation of HPGD induces prostaglandin-driven inflammation, both of which are critical for tumor progression." (PMID 40626022, 2025). "We used TISIDB database to predict and analyze the correlation between CHSY1 expression and immune factors including PD-L1, PD1, LAG3, IDO1 and CTLA4, so that we could observe the interaction between CHSY1 and the CRC tumor microenvironment." (PMID 37749638, 2023). "Importantly, we demonstrate that CHSY1 selectively modulates PDGFRA signaling, and that survival of a mouse model of a CHSY1-expressing tumor is increased by using a PDGFR inhibitor." (PMID 32019907, 2020).
tumor (continued). "Moreover, it was demonstrated that MCM8 may regulate the expression of CHSY1 through affecting its NEDD4-mediated ubiquitination, both of which synergistically execute tumor promotion effects on CRC." (PMID 37710286, 2023). "Based on the RNA screening performing on CRC cells with or without MCM8 knockdown and the following IPA analysis, CHSY1 was identified as a potential target of MCM8 in CRC, whose expression was also found to be higher in tumor tissues than in normal tissues." (PMID 37710286, 2023).
cancer (10 papers, 2015 to 2025). A tumor composed of atypical neoplastic, often pleomorphic cells that invade other tissues. "Moreover, the upregulation of CHSY1 not only enhances CS formation on cancer cells, but is also positively associated with poor patient outcomes." (PMID 34944101, 2021). "Bar and violin plots showed relatively high expression of CHSY1 in the total sample analysis of cancer cell clusters." (PMID 37749638, 2023). "According to dot plots, CHSY1 was significantly upregulated in the cancer cell population of primary CRC tissue compared to samples from different parts of the body." (PMID 37749638, 2023). "The primary and secondary lesions and corresponding paracancerous tissues of four patients with CRC liver metastases were first detected by immunofluorescence, and the results showed that CHSY1 expression in cancer tissues was higher than that in paracancerous tissues." (PMID 37749638, 2023). "However, the specific CSPGs involved in the CHSY1-regulated malignant phenotypes of cancer cells are yet to be explored." (PMID 34944101, 2021). "Thus, to explore the CS-associated pathways in human GBM, we analyzed genes co-expressed with CHSY1 in the TCGA dataset using the cBioPortal for cancer genomics." (PMID 34944101, 2021). "Moreover, recent studies have revealed the role of CHSY1 in several types of malignant tumors." (PMID 37710286, 2023). "We found that three chondroitin synthases (CHSY1, CHSY3, and CHPF) were upregulated in both cancer tissue and placenta, indicating an important role of ofCS chains length for VAR2CSA binding." (PMID 34966741, 2021). "The similarly up-regulated chondroitin synthases (CHSY1, CHSY3, and CHPF) in both cancer tissue and human placenta indicate an important role of the proteoglycan CS chains length for Plasmodium falciparum VAR2CSA protein binding." (PMID 34966741, 2021). "Thus, knockdown of CHSY1 suppressed CD8+ T cell exhaustion and enhanced the expression of CD4+ T and CD8+103+T cells to kill cancer." (PMID 37749638, 2023). "Three chondroitin synthases (CHSY1, CHSY3, and CHPF) were upregulated in both cancer and placenta, indicating the length of ofCS chains might be an important factor for VAR2CSA binding." (PMID 34966741, 2021).
CHSY1 also shares sentences with these, for which no sentence is quoted: gastric cancer (3 papers); bladder cancer (2); breast cancer (2); glioblastoma (2); benign tumors (1); colon adenocarcinoma (1); colon cancer (1); COVID-19 (1); genetic disorders (1); lymph node metastasis (1); malignant peripheral nerve sheath tumor (1); mental retardation (1); Metabolic Disorder (1); myxofibrosarcoma (1); prostate tumour (1); rectum adenocarcinoma (1); renal fibrosis (1); soft tissue sarcoma (1); temtamy preaxial brachydactyly syndrome (1); Thyroid adenoma (1).